TREM2 (triggering receptor expressed on myeloid cells 2)
Diseases named in the same sentence as TREM2 in open-access papers (continued):
Sharing a sentence is not in itself a finding about the gene and the disease.
tumor (continued). "While we commonly observe TREM2-associated proliferative BCC and BST in human and murine BCCs, the variable abundance of BIT cells in BCC patients and murine tumors argues for a specialized role of the TREM1-associated inflammation in driving high levels of NF-κB signaling in tumor epithelium." (PMID 39289380, 2024). "However, recent evidence suggests TREM-2 may suppress antitumor immunity and facilitate tumour immune evasion within the TME." (PMID 39684475, 2024). "Notably, TREM2+ Macrophages promoted the transition of CD4+ T cells into an anti-tumor phenotype through inhibitory receptors such as PDL2 and other inhibitory receptors, while CD4_Tcm further enhanced the differentiation of TREM2+ Macrophages into a tumor-promoting phenotype via the TGF-β pathway." (PMID 38948071, 2024). "Similarly, ELISA results showed consistently increased granzyme B and perforin in the tumor-grinding fluid of mice injected with TREM2 KO monocytes, indicating that TREM2 promotes tumor growth in vivo by increasing the number of M2-TAMs and inhibiting the anti-tumor function of CD8+ T and NK cells." (PMID 39135069, 2024). "Surprisingly, LLC CM significantly reduced the phagocytic activity of WT BMDMs similar to that of TREM2 KO BMDMs, indicating that the tumor cell-CM may have transformed the phenotype of the macrophages, resulting in a reduction in macrophage function, including phagocytosis." (PMID 39135069, 2024). "Therefore, we defined the tumor C1Q+ macrophages as TREM2+ TAMs." (PMID 37187751, 2023). "Similarly, the combination of TREM2 and its ligand not only promotes tumorigenesis, progression, and the high expression of CD163 in tumor-associated macrophages but also amplifies the inflammatory response in the local tumor microenvironment." (PMID 36741909, 2023). "This TREM2+ cluster was enriched for genes linked to pro-tumor pathways and could strongly interact with FOXP3+ Tregs through the IL1B/IL1R interaction, suppressing the anti-tumor effects." (PMID 38066642, 2023). "In this study, we found that SUCNR1, C3aR1, C5aR1, MMP14, THBS 1, TSP-1, and TREM2, which are abnormally expressed in tumor tissue in situ, may be potentially associated with lymph node metastasis." (PMID 37744272, 2023). "Previous work on TREM2+ cells has focused mainly on the immunoregulatory properties of myeloid lineages in the tumor microenvironment, emphasizing their role in preventing the activity of tumor-infiltrating effector lymphocytes or regulating the surrounding tumor-associated inflammatory environment." (PMID 37164949, 2023). "Notably, TREM2 expression is elevated in numerous tumors, with its mRNA levels markedly increased in IDH1/2 wild-type GBM when contrasted with normal tissue, indicating a positive correlation between TREM2 expression, the tumor grade, and an unfavorable prognosis in GBM patients." (PMID 38203185, 2023). "When we examined the Cd11b+Cd45.2+ fraction of cells in the P0 tumor, we noted a Trem2+ percentage anywhere from 50-75%, but when we looked at the Cd11b+Cd45.2+ in the P1 or P2 tumors, we noticed a significant increase relative to the quantity of Trem2-Cd45.2+ cells." (PMID 37164949, 2023). "Furthermore, anti-TREM2 mAb combined with anti-PD1 inhibited tumor growth and promoted regression, demonstrating that anti-TREM2 therapy may broaden the arsenal of myeloid cell targeting in tumors." (PMID 37187751, 2023). "Furthermore, we noted reduced Ki67+ tumor epithelial cells within the anti-Trem2 treated tumors." (PMID 37164949, 2023). "Therefore, targeting TREM2 and PD-1 enhances the anti-tumor effects of CAR-T." (PMID 37563723, 2023). "Although these studies indicate TREM2 is expressed on tumor associated macrophages (TAMs), the conclusions of these studies do not exclude that other cell types in the tumor might also express TREM2." (PMID 36119485, 2022).
tumor (continued). "Tumor-associated myeloid cells exhibited higher transcriptional expression of molecules linked to the “find me” (G2A), “eat me” (CD93, TIM1, SCARF1, SLC2A1, GAS6, TREM2, AXL, C1QA), and downstream processing (NR1H3, ATG7, PPARG, ABCA1, PPARD, DOCK180) phases of efferocytosis." (PMID 36439171, 2022). "Therefore, TREM2 may be involved in tumorigenesis through mechanisms, such as induction of damage and regulation of tumor immunity." (PMID 36438899, 2022). "Together these data suggest that epithelial TREM2 may support tumor suppressing activity in CRC." (PMID 36119485, 2022). "Similarly, modulation of TAM function via TREM2 (Triggering Receptor Expressed On Myeloid Cells 2) inhibition or small-molecule inhibitors of phosphatidylinositol 3-kinase γ (PI3Kγ) also relies on combination with CPI to demonstrate tumor growth regressions in preclinical models." (PMID 35179953, 2022). "However, depending on the role in tumor cells, blockade of TREM2 may still be clinically unfavorable." (PMID 36119485, 2022). "Furthermore, Maf, Atf3, and Hif1a are potential regulators of regulatory myeloid (Mreg) cells, while Hif1a is a potential regulator of tumor-associated macrophages in MCA205 mouse tumors; these two myeloid subpopulations share the expression of Arg1 and Trem2 (Arg1+Trem2+)." (PMID 35359989, 2022). "In addition, an increasing number of research show that TREM2 plays a role in tumor progress." (PMID 36713360, 2022). "However, the function of T cells against tumor cells was negatively correlated with TREM2, suggesting that TREM2 may suppress tumor immunity." (PMID 36713360, 2022). "As noted, TREM2 expression by myeloid cells can impact T cell activation and proliferation; thus, it is not surprising that TREM2 may be able to serve as a biomarker for tumor burden and high TREM2 expression may confer resistance to immune checkpoint therapy (ICT)." (PMID 36119485, 2022). "Therefore, the Kaplan Meier plots may be useful as a starting point to evaluate overarching trends, but not as useful for the purpose of delineating the specific role of TREM2 within the epithelial tumor cells versus the immune cells in the TME." (PMID 36119485, 2022). "This could suggest that TREM2+ macrophages might be engaged in closer bidirectional interactions with tumor cells, being therefore more exposed to tumor-derived immunosuppressive factors, and in turn affecting tumor cell survival, proliferation, and invasiveness." (PMID 35746551, 2022). "Trem2 was not discerned by IHC in our FFPE liver tissues from C3H/He mice (data not shown).The number of CD44+ macrophages was strongly associated with the development of tumours and tumour number." (PMID 34408183, 2021). "Thus, this balance of pro-inflammatory TREM-1 to anti-inflammatory TREM-2 might, in part, control the phenotype and function of tumor-infiltrating myeloid cells." (PMID 35223446, 2021). "Therefore, TREM2 reduces tumor progression in vivo by directly improving NK cell cytotoxicity, and TREM2-overexpressing DCs and macrophages could develop and stimulate NK cell function in vivo." (PMID 33980160, 2021). "In addition, tumor-bearing SAMs displayed a high expression of complement C1q A chain and B chain (C1qa and C1qb) and triggering receptor expressed on myeloid cells 2 (Trem2), and a low expression of the major histocompatibility complexes (Cd74, H2-D1, H2-Aa, and H2-Eb1) compared with control SAMs." (PMID 33782087, 2021). "Importantly, TREM2 protein levels decreased gradually in a tumor stage-dependent manner." (PMID 31489935, 2019). "Interestingly, more TREM-2+DCs and TREM-2+MΦs were harvested from such medium than that from the normal medium (NM), indicating that tumor microenvironment could induce TREM-2." (PMID 27102437, 2016). "First, we describe important subpopulations of profibrotic and pro-tumor macrophages, including SPP1+, MERTK+, TREM2+, and MARCO+ cells, using high-resolution spatial and single-cell omics technologies." (PMID 41939908, 2026).
tumor (continued). "Three human CRC specimens were selected to validate such discovery by assessing the co-expression of TREM2 and macrophage marker CD163 in tumor tissue." (PMID 39744236, 2025). "Blocking TREM2 signaling promotes cross-presentation of tumor antigens, boosts CD80/CD86 levels, and synergizes with anti–PD-1 therapy to control tumor growth." (PMID 40821795, 2025). "In summary, TREM2+ macrophages induced by TGF-β1 play a driving role in HCC progression by suppressing CD8+ T cells and promoting tumor cell glycolysis." (PMID 39838454, 2025). "In the tumor microenvironment (TME), TREM2+ macrophages display a transcriptional program enriched for immunosuppressive mediators such as IL-10, TGF-β, and arginase-1 (ARG1), and show reduced expression of antigen-presentation molecules (e.g., MHC-II)." (PMID 40821795, 2025). "In vitro experiments have further confirmed that TREM2+ macrophages can inhibit T cell activation and the secretion of IFN-γ, thereby contributing to tumor immune escape." (PMID 40242752, 2025). "We show that HAVCR2 + ADAM + myeloid cells have increased transcription of TREM2 and APOE, which have been proposed as pro-tumor macrophage markers." (PMID 39953623, 2025). "Targeting TREM2-related signaling pathways with fostamatinib R788 can induce EAC cell death and growth arrest, reduce tumor burden, and demonstrate anti-tumor effects in xenografted mouse models." (PMID 40242752, 2025). "We also investigated the impact of targeting myeloid cell checkpoints together with T cell checkpoints on tumor growth by using anti-IL1B, anti-TREM2 or anti-IFITM, alone or in combination with anti-PD-1/CTLA4/LAG3." (PMID 40027748, 2025). "The number of antibody doses and time needed to achieve complete response and tumor elimination was reduced when using multiple ICB and anti-TREM2 compared to anti-PD-1 alone, limiting mice exposure to potential chronic adverse events." (PMID 40027748, 2025). "Our study leveraged ART to target TREM2 in TAMs, therefore activating their intrinsic STING signaling cascades in macrophages to restore the anti-tumor effect of macrophages and mutually reverse immunosuppression." (PMID 39744236, 2025). "Genetic deletion or antibody-mediated blockade of TREM2 in HCC models leads to enhanced IL-12 production and antigen presentation capacity, facilitating stronger T cell activation and reduced tumor growth." (PMID 40821795, 2025). "These TREM2+ TAMs can also secrete VEGF-A and other factors that promote angiogenesis and support tumor growth." (PMID 40051497, 2025). "These have proven that utilizing TREM2 inhibitor ART indeed augments the therapeutic outcome of STING agonist MSA-2, and the prodrug GB2 is a promising anti-tumor agent." (PMID 39744236, 2025). "Our results show that strategically targeting TIM3, LAG3, TIGIT, CTLA4, IFITM, TREM2 and PD-1 in MMRd and also MMRp CRC tumors not only further limits tumor growth but can also significantly increase the complete elimination of tumors." (PMID 40027748, 2025). "Immunohistochemistry on tumour biopsy specimens before CAR T‐cell infusion revealed elevated levels of CD163+ and TREM2+ cells in non‐responders compared to responders (p = .0092 and p = .0350, respectively)." (PMID 40268516, 2025). "This study proposes a novel therapeutic strategy by targeting TREM2-expressing TAMs and activating STING to optimize tumor immunity." (PMID 39744236, 2025). "We confirmed that TREM2 overexpression promoted CCL8 secretion, which, in turn, contributed to tumor cell proliferation and migration." (PMID 41253786, 2025). "We disclose that synergistic effect on TREM2 inhibition and STING activation elicits innate and adaptive anti-tumor immunity by reprogramming TAMs." (PMID 39744236, 2025).
tumor (continued). "The TREM2/p-STAT1/CCL8 and PD-L1 axis in TAMs plays a crucial role in tumor progression and resistance to anti-PD-L1 therapy." (PMID 41253786, 2025). "To further investigate the impact of TREM2 on HCC development, we conducted experiments using orthotopic and subcutaneous transplantation tumor models." (PMID 39838454, 2025). "Concurrently, ADM can induce TREM2+ TAMs to release Galectin-1, reducing CXCL9 production thereby inhibiting CD8+ T cell tumor recruitment." (PMID 41450464, 2025). "More importantly, in GC patients, TREM2+ TAMs exclude CD8+ T cell infiltration and promote immune checkpoint expression on tumor-infiltrated CD8+ T cells, like PD-1, CTLA4, and TIM3, which shapes an inhibitory immune microenvironment." (PMID 41253786, 2025). "Based on these results, we classified mac0 as “tumor‐suppressive CD5L+ macrophages” and mac3 as “tumor‐promoting TREM2+ macrophages”." (PMID 40552574, 2025). "Furthermore, LLC CM management promotes the conversion of TREM2+ macrophages to a tumor-promoting M2-like phenotype, suggesting that special molecules in tumor cell-derived CM could regulate the physiological function of TREM2, such as impairing TREM2-mediated phagocytosis." (PMID 39135069, 2024). "TREM2+ LAMs not only promote tumor angiogenesis by facilitating VEGF signaling, but also promote cancer progression by suppressing anti-tumor immune responses, correlating with poor clinical outcomes in HCC patients." (PMID 38725629, 2024). "Further research has shown that TREM2 can modulate TAM phenotype and function, indicating its important role in promoting immune suppression in the tumor microenvironment." (PMID 39113887, 2024). "We identified the highest numbers of outgoing and incoming signaling interactions in BIT tumor state, TREM1 and TREM2 myeloid cells, and dendritic cells, with fewer interactions predicted from T cells and fibroblasts." (PMID 39289380, 2024). "It is noteworthy that, in HCC tissues, TREM2 can both activate the PI3K/Akt signaling pathway to promote tumor progression and inhibit tumor progression by inhibiting the PI3K/Akt/β-Catenin pathway." (PMID 38725629, 2024). "TREM2 overexpression at TAMs in HCC led to a poor prognosis, while TREM2 down-regulation enhanced CD8+ T cell infiltration, hindering tumor growth." (PMID 39408564, 2024). "Overexpression of TREM2 can inhibit the occurrence of EMT by targeting the PI3K/Akt/β-Catenin pathway, thereby inhibiting the invasion and metastasis of tumor cells." (PMID 38725629, 2024). "Among them, the TREM2+ subpopulation was characterized by high expression of GPNMB, TREM2, ACP5, LGMN, and TIMP2, and mainly distributed at the boundary and core region of the tumor." (PMID 38948071, 2024). "Accumulated evidence revealed that LAMs shared a high expression of typical genes (such as APOE, APOC1, GPNMB, TREM2, SPP1 etc.)and played a central role in tumor immunity." (PMID 38346944, 2024). "In contrast, in CRC tissues, TREM2 inhibits the proliferation and metastasis of CRC tumor cells by inhibiting the PI3K/Akt signaling pathway." (PMID 38725629, 2024). "The observed increase in the TREM-1/TREM-2 (%, MFI) ratio and decreased TREM-2 MFI expression indicates a shift toward more pro-inflammatory and tumour-promoting conditions, as demonstrated in patients versus healthy controls (p ≤ 0.001, p = 0.004)." (PMID 39684475, 2024). "According to spatial analyses, TREM2+ macrophages are inside the tumor nest and close to the invasive margin, whereas FOLR2+ macrophages reside away from the tumor nest and remain in the perivascular area." (PMID 37822933, 2023). "When the TREM2 gene was ablated, the abundance of regulatory myeloid immune cells and exhausted CD8+ T cells was significantly reduced, and tumor growth was inhibited." (PMID 37187751, 2023). "The presence of TREM2+CD163+ macrophages suggests an immunosuppressive and tumor promoting phenotype of CRCpMMR TAMs, as previously reported." (PMID 37370706, 2023).
tumor (continued). "To assess the infiltration of TREM2+ TAMs in tumor tissues, we labeled macrophages with CD68 and subsequently observed the expression of TREM2 on this cell type." (PMID 37187751, 2023). "This revealed several strong putative interactions between GBM tumor cell ligands and macrophage receptors that were conserved over the different co‐cultures, including APP:CD74, CD99:PILRA, PTN:ALK, and CLU:TREM2." (PMID 37791581, 2023). "These senescent-like neutrophils overexpress triggering receptor expressed on myeloid cells 2 (TREM2) and are more immunosuppressive and tumor-promoting than canonical immunosuppressive neutrophils." (PMID 37380989, 2023). "The mezzo-forte subtype matched well with metaplastic cancer cells (subtype I), less hijacked by suppressive cells as in the forte subtype, and exploited alternative tumor-promoting TME niches, exemplified by TREM2+ macrophages and tumor-promoting fibroblasts." (PMID 36198671, 2022). "Specifically, SLS-dominant tumors were enriched with M2-like macrophages with high expression of TREM2 and TYROBP, a receptor complex on macrophages recently shown to suppress T-cell function in tumor microenvironment." (PMID 36028490, 2022). "Taken together, these findings demonstrate that TREM2+ LAM-like cells can contribute to microenvironment remodeling and facilitate an immunosuppressive tumor ecosystem." (PMID 35359989, 2022). "TAMs were present in both tumor and metastatic lymph nodes and were defined based on the shared expression of APOE, APOC1, and C1QA-C, and the mutually exclusive expression of TREM2/CADM1 and FOLR2." (PMID 35746551, 2022). "TREM2 genetic blockade or TREM2 targeting with antibodies resulted in improved tumor control, enhanced response to anti-PD1, and significant changes in the tumor immune landscape." (PMID 35746551, 2022). "However, it remains a challenge to locally increase TREM2 expression according to the clinical symptoms and laboratory tests of AD patients while avoiding the toxic effects of activating TREM2-expressing macrophages in other tissues, e.g., tumor growth and immune evasion." (PMID 35658903, 2022). "Among the TAM targets that recently surfaced as critical inhibitors of anti-tumor immunity are the receptors TREM1 and TREM2." (PMID 33815418, 2021). "In a word, more and more evidence indicate that TREM2 acts as a tumor suppressor in modulating TME, and the purposeful and accurate regulation of TREM2 signaling pathway has the potential to reshape the TME and exert a stronger anti-tumor effect." (PMID 34539652, 2021). "Within the tumor site, the likely complex interactions between TREM-1-positive granulocytic cells and their TREM-2-expressing macrophages are yet to be fully dissected." (PMID 35223446, 2021). "Thus, we propose that TREM-1 may serve as a biomarker for tumor progression and a useful target for reprogramming the immunosuppressive tumor microenvironment of the host and that TREM2 might play an important role in balancing the inflammatory signals within the tumor." (PMID 35223446, 2021). "TREM2 is expressed on CSF1R+ TAMs and is modulated by CSF1 and its blockade on TAMs results in delayed tumor growth, remodeling of the tumor immune contexture and increased ICI efficacy." (PMID 34220848, 2021). "In summary, we found that TREM-1 is highly expressed on myeloid cells in tumor-bearing mice and in patients with RCC and that TREM-2 is co-expressed with TREM-1 in MDSC and TAM." (PMID 35223446, 2021). "Similar to our scaffold and primary tumor data, the macrophages in the liver metastases had high expression of C1QA, C1QB, and TREM2 consistent with this macrophage population being part of a systemic response to a primary tumor." (PMID 33782087, 2021). "In this study, we found that both TREM-1 and TREM-2 were expressed on MDSC and TAM and that tumor-bearing mice have elevated levels of sTREM-1 in their blood." (PMID 35223446, 2021).